RAP1B (RAP1B, member of RAS oncogene family)
Diseases named in the same sentence as RAP1B in open-access papers (continued):
Sharing a sentence is not in itself a finding about the gene and the disease.
diabetes (5 papers, 2019 to 2024). "Downregulation of Rap1B to reduce VEGF signal transduction can impede excessive vascular leakage in early diabetes mellitus." (PMID 34028657, 2022). "Inhibition of Rap1B to reduce VEGF signal transduction can prevent excessive vascular leakage in early diabetes mellitus." (PMID 31915515, 2019). "By inhibiting VEGF signal transduction, Rap1B can prevent excessive vascular leakage in early diabetes mellitus." (PMID 31915515, 2019). "Furthermore, Rap1B can prevent excessive vascular leakage in early diabetes mellitus by inhibiting VEGF signal transduction." (PMID 34028657, 2022). "Previous studies have shown that targeting Rap1A and inhibiting T cells infiltration alleviate diabetic peripheral neuropathic pain in mice, and Rap1B may prevent excessive vascular leakage in patients with early diabetes through suppressing VEGF signaling." (PMID 36467890, 2022). "Indeed, Rap1B is required for VEGF-dependent EC junction dissolution in vitro, as well as in vivo under conditions of excessive VEGF in early diabetes, where EC-Rap1B deletion protects against retinal vessel hyperpermeability." (PMID 39337337, 2024).
colon cancer (4 papers, 2014 to 2025). "Our study provides strong support that the vital role of FN1/RAP1B/CREB loop during colon cancer metastasis." (PMID 40638546, 2025). "Taken together, this data demonstrates that FN1 can promote colon cancer metastasis in vivo via RAP1B." (PMID 40638546, 2025). "Based on the bioinformatics analysis of our RNA‐seq data and the GEO dataset, we identified that highly expressed RAP1B enriched the ubiquitination pathway in primary and metastasis colon cancer compared to normal tissues." (PMID 40638546, 2025). "To further deeply investigate the detailed mechanism by which FN1 regulates RAP1B in colon cancer, we detected the expression of Akt/CREB signalling pathway." (PMID 40638546, 2025). "Taken together, our inhibitor and knockdown experiments suggest that veratridine-stimulated invasion by SW620 colon cancer cells is mediated by an SCN5A-dependent pathway involving PKA/RAP1B/MEK/ERK (predominant pathway)." (PMID 26096612, 2015). "The data further suggest that although VGSCs signal through both Rap1A and Rap1B in colon cancer cells, Rap1B activation in particular leads to persistent ERK1/2 MAPK activation." (PMID 26096612, 2015). "Taken together, our results reveal that targeting FN1/RAP1B/CREB‐mediated tumour interactions might be an attractive therapeutic strategy for metastasis colon cancer patients." (PMID 40638546, 2025). "Finally, we also detected the expression of FN1, TIMP1, and RAP1B in ex vivo by establishing the patient‐derived tumour‐like cell clusters (PTCs) from primary and metastatic colon cancer tumour tissues." (PMID 40638546, 2025). "However, there was little research about the role of RAP1B in colon cancer progression and metastasis." (PMID 40638546, 2025). "In colon cancer, miR-30b-5p inhibits metastasis by targeting Rap1b." (PMID 34819077, 2021). "Thus, we investigated the participation of Rap1 in the VGSC signaling in colon cancer cells and found that VGSCs signal through both Rap1A and Rap1B to increase invasion potential." (PMID 26096612, 2015). "We also assessed whether FN1 mediated colon cancer EMT via RAP1B." (PMID 40638546, 2025). "This possibility is further supported by the fact that Rap1B is phosphorylated and activated by PKA44, and VGSC signaling to ERK1/2 requires PKA and Rap1B in colon cancer cells (this study)." (PMID 26096612, 2015). "FN1 enhanced colon cancer cell migration, invasion, and epithelial to mesenchymal transition (EMT) in vitro and promoted liver and lung metastasis of colon cancer in nude mice through RAP1B." (PMID 40638546, 2025). "FN1 promotes colon cancer migration, invasion, EMT and metastasis though RAP1B." (PMID 40638546, 2025). "In conclusion, we provide evidence for VGSCs in colon cancer cells signaling through a novel pathway that is VGCC-independent, cAMP-independent and involves PKA, Rap1B, MEK and persistent activation ERK1/2, leading ultimately to transcriptional induction of invasion-related genes." (PMID 26096612, 2015). "FN1 could regulate colon cancer migration, invasion, EMT, and metastasis by regulating RAP1B." (PMID 40638546, 2025). "To further investigate whether FN1 regulates colon cancer migration and metastasis in vitro through RAP1B, we introduced RAP1B shRNAs in FN1‐overexpression HCT116 cells, and transfected FN1‐knockdown LOVO cells with RAP1B overexpression plasmid." (PMID 40638546, 2025). "Of note, a single miRNA can regulate a multitude of target genes concomitantly; for instance, it has been reported that miR-139-5p suppresses progression of liver cancer by down-regulating Rho-kinase 2; and miR-139-5p could repress the activity of RAP1B and IGF-IR in colon cancer." (PMID 24885920, 2014).
esophageal squamous cell carcinoma (4 papers, 2016 to 2024). Esophageal squamous cell carcinoma (ESCC) is a type of esophageal carcinoma (EC) that can affect any part of the esophagus, but is usually located in the upper or middle third. "This is contrary with the previous report where RAP1B has shown to activate Wnt/beta-catenin signaling in esophageal squamous cell carcinoma." (PMID 34235179, 2021). "RAP1B, a Ras-related small GTP-binding protein that behaves as a GTPase, has been implicated as an oncogene in a variety of tumors, including esophageal squamous cell carcinoma (ESCC), CRC, T-acute lymphoblastic leukemia, non-small cell lung carcinoma, glioma and thyroid carcinoma." (PMID 27729617, 2016). "In the context of esophageal squamous cell carcinoma (ESCC), miR-518b, which acts as a tumor suppressor, induces apoptosis and represses invasion by specifically targeting Rap1b." (PMID 38542153, 2024).
hepatocellular carcinoma (4 papers, 2019 to 2024). A malignant tumor that arises from hepatocytes. "One study reported the associations between hepatitis B virus-related hepatocellular carcinoma and the up-regulation of Rap1b, suggesting its involvement in cellular responses to viral infection." (PMID 39727808, 2024).
Hypertension (3 papers, 2015 to 2021). The presence of chronic increased pressure in the systemic arterial system. "The compound effect of endothelial loss of both Rap1A and Rap1B isoforms is severe endothelial dysfunction and hypertension." (PMID 34222255, 2021). "Endothelial Rap1 deficiency of both Rap1 isoforms, Rap1A and Rap1B, significantly impairs endothelial NO production in vitro and NO-dependent vasorelaxation, leading to endothelial dysfunction and hypertension in vivo." (PMID 34222255, 2021). "Endothelial deletion of the two highly homologous Rap1 isoforms, Rap1A and Rap1B, leads to endothelial dysfunction ex vivo and hypertension in vivo." (PMID 34222255, 2021). "Instead, the most profound defect in total Rap1 (Rap1A + Rap1B), EC-specific KO (Rap1iΔEC) mice is endothelial dysfunction due to a decreased NO bioavailability defect, evidenced by impaired vasorelaxation defect ex vivo and hypertension in vivo." (PMID 34222255, 2021). "Interestingly, the phenotype of total Rap1b-/- mice: hypertension and cardiac hypertrophy, phenocopies that of EC-Rap1a+/-Rap1b-/- mice." (PMID 26714318, 2015).
lung adenocarcinoma (3 papers, 2014 to 2022). A carcinoma that arises from the lung and is characterized by the presence of malignant glandular epithelial cells. "Kaplan–Meier Plotter analysis showed that lung adenocarcinoma patients with positive ATCR2, FHL1, RAB27B, and RAP1B expression had observably longer overall survival than patients with negative expression (P < 0.05)." (PMID 36404333, 2022).
lung carcinoma (3 papers, 2018 to 2024). "Specifically, understanding aberrant 5hmC changes in RAP1B and other genes enriches our understanding of the molecular mechanisms driving lung cancer tumorigenesis, paving the way for novel targeted therapeutic approaches." (PMID 38391911, 2024). "Additionally, our finding of increased 5hmC in RAP1B, a GTP-binding protein associated with poor prognosis in multiple cancers, including lung cancer, indicates potential new directions for therapy, including the use of hypomethylating agents." (PMID 38391911, 2024). "Key genes, including MAPK1, RAP1B, and RAF1, featured prominently in these pathways, underscoring their functional relevance in lung cancer." (PMID 38391911, 2024). "In addition, in lung cancer, miR-30b-5p overexpression could inhibit the progression of lung cancer and enhances cisplatin sensitivity through targeting low-density lipoprotein receptor-related protein 8 and miR-30b-5p functions as a metastasis suppressor in CRC by targeting Rap1b." (PMID 35892081, 2022).
melanoma (3 papers, 2021 to 2024). A malignant, usually aggressive tumor composed of atypical, neoplastic melanocytes. "Of these, PON3, CD14 and RAP1B were evaluated for their association with survival in the primary melanoma sample data set of the TCGA." (PMID 34439311, 2021). "We found that dafadine-A did not affect the proliferation of adherent melanoma cells, but dramatically inhibited cholesterol-induced melanoma spheroid propagation, with downregulation of Rap1A/Rap1B expression and phosphorylated AKT1-thr308/309." (PMID 38775844, 2024). "By proteomics we identified five proteins in plasma CD81sEV that were differentially expressed between HD and stage II (APOA5, PON1, PON3 and CD14) and between HD and stage III–IV, advanced stage melanoma, (RAP1B)." (PMID 34439311, 2021). "To evaluate the relationship among PON3, CD14 and RAP1B and prognoses of melanoma patients, we conducted Kaplan–Meier survival analysis according to gene expression data of PM." (PMID 34439311, 2021). "In contrast, reduced levels of RAP1B were associated with worse prognosis of patients, supporting the reduction of RAP1B we detected in stage III–IV melanoma patients’ CD81sEV." (PMID 34439311, 2021). "In this work, we found that DHCR24 and DHCR24-induced 27HC significantly upregulated Rap1A/Rap1B expression and further activated the PI3K/AKT signaling pathway in melanoma spheroids, while Rap1 agonists or AKT inhibitors reproduced the stem cell phenotypes." (PMID 38775844, 2024). "To explore whether the identified proteins, APOA5, PON1, PON3, CD14 and RAP1B, could be of any clinical relevance, we evaluated their expression in silico in relation to the available clinical information in the TCGA dataset of primary melanoma samples (PM, n = 80)." (PMID 34439311, 2021). "Finally, we confirmed that the effects of cholesterol on melanoma resistance require its metabolite 27HC through CYP27A1 catalysis, and that 27HC further upregulates Rap1A/Rap1B expression and increases AKT phosphorylation." (PMID 38775844, 2024).
viral infection (3 papers, 2022 to 2024). "Although integrin pathway-associated signals downstream of Rap1b activation signals have been extensively investigated as regulators of cytoskeleton-associated activities, few reports link Rap1b with viral infections." (PMID 35138149, 2022). "Altogether, these reports hint at a potential relationship between Rap1b, the cytoskeleton, and viral infection." (PMID 37515145, 2023). "Further investigation indicated that the suppression of Rap1b activation derives from phosphorylated PKA and Rap1b mutants with partial or complete prenylation instead of phosphorylation, which promoted viral infection in a dose-dependent manner." (PMID 37515145, 2023). "Here, we demonstrated that the HSV-1 immediate early (IE) gene ICP4 inhibits protein kinase A (PKA) phosphorylation to induce Rap1b-activation-mediated viral infection." (PMID 37515145, 2023). "Viral titers were rescued via Rap1b plasmid transient overexpression but without a clear dose–response phenotype, even though the total Rap1b protein increased significantly during virus infection." (PMID 37515145, 2023). "After the knockdown of Rap1b expression (≈80%), viral infection was reduced by 90%." (PMID 37515145, 2023). "Furthermore, the PKA agonist Forskolin disturbed Rap1b activation in a dose-dependent manner, accompanied by a decreasing trend in viral infection." (PMID 37515145, 2023). "Overall, these observations suggest that the HSV-1 IE gene ICP4 may dominate or partially promote Rap1b activation during virus infection through the inhibition of PKA phosphorylation." (PMID 37515145, 2023). "Having established a correlation between HSV-1 infection and Rap1b expression, we next assessed whether Rap1b inhibition with siRNA could impair viral infection." (PMID 37515145, 2023). "Previous studies have shown that crosstalk pathways led by downstream CDC42 play a decisive role in membrane remodeling during viral infection in the Rap1b-triggered cascade signaling pathway, which significantly differs between enveloped and non-enveloped viruses." (PMID 37515145, 2023). "Although it remains unclear how interactions between viral capsids and Rap1b lead to enhancement of PKA- and SmgGDS-dependent Rap1b activation, these results underscore the importance of Rap1b in virus infection." (PMID 35138149, 2022). "After screening five HSV-1 IE genes, we determined that ICP4 is likely responsible for the activation of Rap1b, and this is achieved by inhibiting the activation of the phosphorylation restriction factor PKA, allowing for effective viral infection." (PMID 37515145, 2023). "Altogether, we show the significance of Rap1b during HSV-1 infection and uncover the viral infection mechanism determined by the posttranslational regulation of the viral ICP4 gene and Rap1b host protein." (PMID 37515145, 2023). "Treating the cells with Rap1b small interfering RNA (siRNA) showed a dose-dependent decrease in viral infection levels, but no dose-dependent increase was observed after Rap1b overexpression." (PMID 37515145, 2023). "The correlation between Rap1b activation and a specific IE gene has not yet been obtained, and all five IE genes exhibited the ability to promote viral infection." (PMID 37515145, 2023). "Furthermore, dephosphorylation of PKA during HSV-1 infection was induced, and the employment of PKA agonists and inhibitors affected virus infection by inhibiting and promoting Rap1b activation with a negative correlation, respectively." (PMID 37515145, 2023). "However, total Rap1b protein expression was not upregulated in IE transfected cells without virus infection, implying that Rap1b translation is driven by separate mechanisms." (PMID 37515145, 2023). "However, this study detected no dose-dependent increase in virus infection or Rap1b activation with a gradient increase in Rap1b expression in the HSV-1-infected cells." (PMID 37515145, 2023).
viral infection (continued). "However, all five HSV-1 IE genes promoted virus infection to different degrees in overexpressing cell lines, with a similar impact on Rap1b activation, which could not clarify whether Rap1b activation was driven by IE genes or a signaling cascade reaction initiated by rapid virus infection." (PMID 37515145, 2023).
atherosclerosis (2 papers, 2025). A disease characterized by the build-up of fatty material and calcium deposition in the arterial wall resulting in partial or complete occlusion of the arterial lumen. "In atherosclerosis-prone regions, Rap1B-deficient mice (inducible VE-cadherin-Cre knockout) exhibit increased plaque burden and leukocyte accumulation, highlighting its role in maintaining vascular homeostasis." (PMID 40508181, 2025). "Together, these findings redefine the roles of Rap1A and Rap1B in endothelial biology and highlight their relevance in diseases such as tumor angiogenesis, atherosclerosis, and inflammatory lung injury." (PMID 40508181, 2025). "The KEGG path view suggests that LBP, MMP9, APOB, IL6, and RAP1B are involved in lipid metabolism and atherosclerosis." (PMID 41221287, 2025). "Rap1B is a key regulator of VEGFR2 signaling, promoting angiogenesis, nitric oxide production, and immune evasion in tumors while restraining proinflammatory signaling in atherosclerosis." (PMID 40508181, 2025).
endometrial cancer (2 papers, 2022). Primary or metastatic malignant neoplasm involving the endometrium (mucous membrane that lines the endometrial cavity). "Direct interaction between RAP1B mRNA and miR-28-5p has already been demonstrated in endometrial cancer cells." (PMID 35632705, 2022). "As another example, Lnc LOXL1-AS1 can be used as a ceRNA to compete with RAP1B mRNA for binding with miR-28-5p to promote RAP1B expression, ultimately inhibiting apoptosis of endometrial cancer cells." (PMID 36380019, 2022). "On the contrary, it has been reported that in endometrial cancer cells, the lncRNA LOXL1-AS1 sequesters miR-28-5p and induces the overexpression of its target RAP1B." (PMID 35632705, 2022).
endometriosis (2 papers, 2014 to 2017). The growth of functional endometrial tissue in anatomic sites outside the uterine body. "The increased expression of Rap-1b has been found in women with endometriosis as compared to early secretory phase endometrium from fertile women and, is regulated via RAS/RAF/MAPK and PI3K pathways." (PMID 25405865, 2014).
liver cancer (2 papers, 2014 to 2022). An epithelial or non-epithelial malignant neoplasm that arises from the liver. "In contrast, the increased Rap1b expression by miR-101-3p suppression enhanced HCC in various liver cancer cell lines." (PMID 36555545, 2022).
ovarian tumor (2 papers, 2015 to 2017). "In agreement with our previous observation, we observed that GC-mediated signaling induced the expression of miR-708, leading to the depletion of Rap1B and suppression of abdominal metastasis in ovarian tumor-bearing mice with an intact immune system." (PMID 28591224, 2017). "Clinically, low miR-708 and high Rap1B are found in late-state ovarian tumours, as compared with normal, and patients with high miR-708 show significantly better survival." (PMID 25569036, 2015). "Western blot analysis from orthotopic primary ovarian tumours revealed that DEX treatment reduced the Rap1B protein level in the GFP–DEX group, correlated with our in vitro observation that expression of Rap1B was reduced in the presence of DEX." (PMID 25569036, 2015).
pancreatic cancer (2 papers, 2020 to 2021). "This study is the first to characterize the oncogenic function of the long noncoding RNA LINC00514 in pancreatic cancer progression by acting as a competing endogenous RNA (ceRNA) of miR-28-5p to upregulate Rap1b expression." (PMID 32771045, 2020). "Mechanistically, LINC00514 accelerated pancreatic cancer progression via the miR-28-5p/Rap1b axis." (PMID 32771045, 2020). "Downregulation of Rap1b could inhibited the effect of LINC00514 on the proliferation, migration, and invasion in pancreatic cancer cells." (PMID 34346294, 2021).
acute myeloid leukemia (1 paper, 2025). Acute myeloid leukemia (AML) is a group of neoplasms arising from precursor cells committed to the myeloid cell-line differentiation. "USP32 promotes the malignant behaviors of acute myeloid leukemia cells by regulating the stability of Rap1b." (PMID 40136417, 2025).
Burkitt lymphoma (1 paper, 2010). A rare form of malignant mature B-cell non-Hodgkin lymphoma. "Expression of the constitutively active human Rap1B-retro in cells like those derived from Ramos Burkitt's lymphoma and bone marrow from a patient with myelodysplastic syndrome (MDS) warrants further investigation into its role in disease development." (PMID 20170508, 2010).
cardiomyopathy (1 paper, 2022). A disease of the heart muscle or myocardium proper. "The components of the MAPK pathway, such as MAP2K1 through MAPK3, as well as the Ras-related proteins, RAP1A, RAP1B, and M-Ras, had a median 2.6-fold (IQR, 2.0-fold to 15.5-fold) upregulation among patients with SARS-CoV-2 infection compared with patients with noninflammatory cardiomyopathy." (PMID 34910083, 2022).